INS (insulin)
Diseases named in the same sentence as INS in open-access papers (continued):
Sharing a sentence is not in itself a finding about the gene and the disease.
breast cancer (continued). "The insulin and IGF1 receptors have important roles in breast cancer; IGF signaling is important in mammary gland development and metastatic pathways, and its receptor is overexpressed and hyperphosphorylated in breast cancer." (PMID 36012147, 2022). "Reducing these with docosahexaenoic acid (DHA) abrogated insulin-stimulated FASN expression, suggesting insulin promotes FASN expression in breast cancer by upregulating SREBP through the Akt pathway." (PMID 35448537, 2022). "As known, an increment of insulin and the IGF-1 are related to cancers, such as breast cancer and colon cancer." (PMID 35299970, 2022). "In human breast cancer cell lines MCF7, MDA-MB-231 and BT-474, the number and expression of SAM68 protein was increased under leptin or insulin stimulation, and insulin and leptin can stimulate SAM68 tyrosine phosphorylation." (PMID 36059653, 2022). "Insulin-IGF signaling is a key regulator of mammary epithelial progenitors, and higher activity of this signaling pathway increases human breast cancer risk." (PMID 36476730, 2022). "Insulin levels, adipocytokines, and inflammatory mediators trigger benign breast disease (BBD) and breast cancer (BC)." (PMID 35627631, 2022). "Breast cancer models of activated PR lost the expression of IGF1R and acquired insulin hypersensitivity with tamoxifen insensitivity." (PMID 33144693, 2021). "We have previously reported the lipogenic effect of insulin on SREBP1 induction and cell growth in liver and breast cancer cells." (PMID 34575972, 2021). "PAX6 inhibits the viability, migration, and invasion of human breast cancer MCF-7 cells, whereas CADM1 inhibits insulin secretion in INS-1 cells and primary cells." (PMID 33897780, 2021). "The IGF/insulin and ER pathways, through which MHT mainly functions, are interconnected in breast cancer." (PMID 34606580, 2021). "SNAI2 is a direct target of the glucocorticoid receptor GR that regulates cell migration in breast cancer, while PTPN6 is involved in glucose homeostasis via negative regulation of insulin signalling." (PMID 33513136, 2021). "They reported that metformin decreased insulin, glucose, leptin, C-reactive protein (CRP), HOMA-IR, and Ki-67 levels, which attenuated the outcome in breast cancer patients." (PMID 33917520, 2021). "At physiological concentrations, insulin increases the rate of DNA, RNA, and protein synthesis in MCF-7 human breast cancer cells." (PMID 34440224, 2021). "In obese post-menopausal women, there are increased levels of plasma insulin and insulin-like growth factor-1 (IGF-1) that have mitogenic effects on breast cancer cells." (PMID 33482868, 2021). "We experimentally validated the last prediction by chemically inhibiting ribosomal protein S6 kinase in breast cancer cells and then treating them with IGF1 and insulin, as described in Methods." (PMID 34191793, 2021). "The pathways involved in the progression of breast cancer were the MTOR signaling pathway, estrogen signaling pathway, P13-AKT signaling pathway, TGF-β signaling pathway and the insulin signaling pathway." (PMID 33593445, 2021). "A previous study showed that a ketogenic diet applied to reduce blood glucose levels combined with PI3K inhibitors has great potential for preventing insulin feedback, which in turn activates AKT for breast cancer therapy." (PMID 34433808, 2021). "Genome-wide analyses of the mechanisms of action of insulin and IGF1 in breast cancer, as well as identification of the signaling pathways involved, is expected to be of major translational relevance." (PMID 32733384, 2020). "Nar inhibited the proliferation of breast cancer (MCF-7) cells by blocking insulin stimulated glucose uptake in GLUT4 (insulin responsive glucose transporter) expressing, insulin responsive MCF-7 cells." (PMID 33192517, 2020).
breast cancer (continued). "Given the differences in circulating insulin levels and tumor IR expression between Black women and White women, it will be important in future studies to explore whether lowering insulin levels or targeting IR signaling will improve breast cancer survival disparities." (PMID 32393319, 2020). "A significant volume of clinical and epidemiological data provides support to the concept that insulin and the insulin receptor (INSR) have an important role in breast cancer." (PMID 32637033, 2020). "A large body of clinical, experimental and epidemiological data supports the concept that activation of the insulin and IGF1 signaling pathways is a critical requisite for breast cancer progression." (PMID 31771180, 2019). "PTC-209 treatment inhibited a number of signaling pathways including those involved in insulin signaling, DNA damage response and wnt/pluoripotency in the MDA-MB-231 breast cancer model." (PMID 31548560, 2019). "They examined the efficacy of metformin on human breast cancer cells (MCF-7), which is known to be sensitive to insulin and IGF." (PMID 31534778, 2019). "We believe that IGFRs and hybrid receptors are responsible for insulin effects on these RCC cells, as it was recently shown for breast cancer cells." (PMID 30929166, 2019). "Biochemical and molecular dissection of the mechanisms of action of insulin and IGF1 in breast cancer will be of major translational impact." (PMID 31771180, 2019). "In vitro, insulin analogue stimulation increases proliferation of breast cancer cells due to enhanced IGF1R (and INSR) signaling, while exposure to human insulin showed low mitogenic potential." (PMID 29486734, 2018). "Insulin was found to favour growth of breast cancer cells, and insulin increases proliferation of the MCF-7 breast cancer cell line, and IGF1 is a potent mitogen for osteosarcoma cells." (PMID 28316059, 2017). "A study from the Netherlands reported an elevated risk for breast cancer when using cumulative durations without differentiation between them, thus ignoring an imbalance between comparators in the follow-up times (median of 2.2 years for insulin glargine users and 3.8 years for human insulin users)." (PMID 28573394, 2017). "This study also demonstrated that human insulin can promote MCF-7 and T47D breast cancer cell proliferation in a dose- and time-dependent manner, findings consistent with those reported in the literature." (PMID 28427228, 2017). "In MCF-7 human breast cancer cells, IR and DDR1 co-immunoprecipitated and co-localized after insulin or IGF-2 stimulation." (PMID 28591735, 2017). "It has been shown that insulin can induce ER and PR expression, which leads to increased binding capacity of ER in MCF-7 breast cancer cell line." (PMID 28076434, 2017). "Here, we show for the first time that ATF5 is also upregulated after exposure to either insulin or IGF-I and suggest that the ATF5 can also mediate the proliferative effects of the two ligands, which can subsequently lead to an increased mammary tumor growth." (PMID 28785242, 2017). "In summary, this study demonstrates that DDR1 associates with the IR, enhances the activation of IR downstream signaling and the mitogenic and pro-invasive effects of insulin and IGF-2 in breast cancer cells." (PMID 28591735, 2017). "Insulin and IGF-1 receptors are frequently expressed in breast cancer cells, with evidence that their signaling pathways are of crucial importance in the role of breast cancer tumorigenesis, also in the case of TN tumors." (PMID 25916213, 2016). "Increased level of insulin and IGF-1 in central obesity were mitogenic agents and promoted breast cancer cell proliferation directly." (PMID 27247890, 2016). "We propose that the identification of the mechanism linking the IGF-1/insulin signal and AGR2 promoter activation is important, because it provides insights into the development of anti-breast cancer drugs." (PMID 25956506, 2015).
breast cancer (continued). "Thus, metformin may diminish the stimulatory effects of insulin on breast cancer." (PMID 25849721, 2015). "Crosstalk between the insulin/IGF system and ER signaling pathway has been well-established, and IGF-IR is a known mediator of endocrine therapy resistance in breast cancer." (PMID 26029167, 2015). "Some studies showed a strong relationship between insulin glargine and breast cancer, particularly in T2DM patients treated with insulin for more than 5 years." (PMID 25866823, 2015). "The insulin/IGF system has very potent mitogenic, survival, and pro-migratory properties for breast cancer cells in vitro and in animal models [for reviews, see Ref." (PMID 26106366, 2015). "Insulin/Insulin like growth factor 1 (IGF-I) and estrogens have potent positive effects on cell proliferation in breast cancer." (PMID 25034939, 2014). "Results identify that the insulin resistant group displayed alterations in both measures of insulin-glucose homeostasis and CRP, two significant predictors of breast cancer outcome." (PMID 23855321, 2013). "Growth and progression of orthotopic- and genetically-induced mammary tumors in female MKR mice were accelerated as compared to controls, but were blocked using pharmacological inhibitors of insulin signaling or insulin-sensitizers." (PMID 22226054, 2012). "Using this method, we studied the pharmacological profile of IGF1, insulin and insulin analogues on PIP3 production in MCF-7 and MDA-MB231 breast cancer cells." (PMID 22848683, 2012). "The results presented in this work strongly suggest that the glucose- and insulin-induced changes in proliferation and migration of MDA-MB-468 breast cancer and SW480 colon cancer cells are mediated by changes in Akt and/or PLCγ signaling." (PMID 22554284, 2012). "Our data show how glucose and insulin change proliferation and migration capacity in MDA-MB-468 breast cancer and SW480 colon cancer cells in vitro." (PMID 22554284, 2012). "Physical activity may protect against breast cancer through hormonal mechanisms, either directly through influencing circulating hormones or protein levels, or indirectly by reducing body mass resulting in lower levels of circulating sex hormones, or by increasing insulin sensitivity." (PMID 23397025, 2012). "Work with another human breast cancer cell line, MCF-7, has demonstrated that LIV-1 expression is induced by estradiol, IGF-1 and IGF-2, as well as by insulin." (PMID 22852056, 2012). "It is important to remember that IGF-1 is much more mitogenic than insulin, and an insulin concentration 100 times that of IGF-1 was needed to elicit equivalent breast cancer cell growth." (PMID 21773024, 2011). "It is presumed that estrogen and insulin/IGF-1 regulate c-Myc and cyclin D1 during breast cancer cell proliferation." (PMID 19865540, 2009). "Studies have shown that both insulin and IGF-1 exert a mitogenic effect by stimulating cell proliferation and inhibiting apoptosis of breast cancer cells." (PMID 16168130, 2005). "In non-diabetic early-stage breast cancer patients, administration of metformin significantly improved insulin sensitivity and reduced serum insulin levels." (PMID 40374694, 2025). "Using models of endometrial and breast cancer, we evaluated the efficacy of a multi-node PI3K/AKT/mTOR pathway inhibitor approach utilising the dual mTORC1/mTORC2 inhibitor sapanisertib, PI3Kα inhibitor serabelisib and an insulin-supressing diet." (PMID 40360883, 2025). "Our results showed that patients with breast cancer have significantly higher insulin levels than those without breast cancer, which is consistent with the previous evidence." (PMID 38904041, 2024). "Whole grain foods, unlike refined foods, stabilise glycaemic and insulin levels, thus preventing the increase in the concentration of insulin-like growth factor-1 IGF-1, a risk factor for breast cancer." (PMID 38275908, 2024).
breast cancer (continued). "We note that our findings are only generalizable to postmenopausal women who are not taking hormone replacement therapy or exogenous insulin and have no personal history of cancer (including breast cancer)." (PMID 38363402, 2024). "These improvements in metabolic health could have a beneficial impact on tumor outcomes since insulin and IFG-1 can contribute to breast cancer promotion and metastasis." (PMID 38543182, 2024). "None of the screened breast cancer cell lines showed EphA2 protein regulation after insulin stimulation." (PMID 39572596, 2024). "Metformin has been shown to improve insulin sensitivity and reduce circulating insulin in nondiabetic breast cancer subjects." (PMID 38279016, 2024). "Drugs that lower circulating glucose and insulin levels, in particular metformin and SGLT2 inhibitors, have been proposed as treatments for breast cancer and could potentially synergise with ET by reducing PI3K–AKT–mTOR signalling." (PMID 39251829, 2024). "Although, how physical activity mechanistically exerts this influence on breast cancer has not completely been understood, physical activity has been shown to modulate estrogen and insulin signaling." (PMID 39304951, 2024). "Therefore, the potential impact of artificial sweeteners on insulin and IGF pathways is an important area of investigation regarding their role in hormonal disturbances and breast cancer development." (PMID 39767777, 2024). "In several studies, postmenopausal women that were considered “metabolically unhealthy” using different approaches (e.g. high fasting insulin, high HOMA-IR, hepatic steatosis), had elevated breast cancer risk irrespective of BMI." (PMID 37800138, 2023). "In the context of the insulin/IGF system, hyperglycemia and glucose metabolism deregulation have been reported to promote cell proliferation, invasion, migration, and chemotherapy resistance in breast cancer." (PMID 37361518, 2023). "The results of the combined survival analyses showed that the inflammatory insulin combination of LCR&LHR and CAR&LHR could differentiate the prognosis of breast cancer patients." (PMID 36922570, 2023). "The ability of ENDX at 5 μM, but not at 0.01 or 0.10 μM, to block insulin-stimulated AKTSer473 phosphorylation was also observed in the ERα+/HER2- T47D breast cancer cells under serum starved conditions, with TAM and ICI again failing to block insulin-stimulated AKTSer473 phosphorylation." (PMID 38114522, 2023). "Insulin may cross-bind to insulin-like growth factor-I (IGF-1) receptors on breast cells, and downstream signaling pathways provide proliferation stimuli to breast cancer cells." (PMID 37467012, 2023). "Some clinical trials have administrated metformin on non-diabetic breast cancer women, ending with a significant reduction of both insulin and testosterone levels." (PMID 38057926, 2023). "Therefore, SAM68 not only mediates cell metabolism stimulated by insulin and leptin, but also participates in leptin- and insulin-dependent activation of MAPK and PI3K signaling pathways in breast cancer cells." (PMID 36059653, 2022). "The primary advance of the current study is its assessment of which genetic drivers of breast cancer may be most responsive to SGLT2 inhibitors and perhaps other insulin-lowering agents." (PMID 35595952, 2022). "In another study performed on non-diabetic women with adjuvant (early-stage) breast cancer, metformin decreased the level of insulin by 22%." (PMID 36233373, 2022). "The analysis results suggested that the up cluster was significantly related to the functions of oncogenesis and metabolic reprogramming processes of breast cancer, such as the PI3K − Akt signalling pathway, MAPK signalling pathway, insulin secretion, and regulation of hormone secretion." (PMID 35562758, 2022). "A meta-analysis of RCTs for those with breast cancer showed significant improvement in insulin, glucose, and BMI despite no significant dose-response relationship between metformin and these biomarkers." (PMID 36260549, 2022).
breast cancer (continued). "Although primarily used to reduce gluconeogenesis and increase insulin sensitivity in patients with type 2 diabetes, some, but not all, observational studies have reported lower incidence of breast cancer among diabetic patients taking metformin." (PMID 33859943, 2021). "Here, the authors show that restricting when mice eat, but not what or how much they eat, delays breast cancer initiation and reduces tumor growth in obese mice in addition to improving insulin sensitivity and restoring circadian rhythms." (PMID 33495474, 2021). "No other significant associations with all-cause mortality, breast cancer-specific mortality, and breast cancer recurrence were observed for IGFBP3, IGF1/IGFBP3 ratio, insulin, and C-peptide." (PMID 32974138, 2020). "A recent study reported that postmenopausal women who have received aromatase inhibitors for the treatment of breast cancer exhibited higher body fat percentage and insulin resistance than control subjects without a history of breast cancer." (PMID 31941004, 2020). "Together this data indicates that BCATc regulates TNBC cell proliferation, migration and invasion through the IGF-1/insulin PI3K/Akt pathway, culminating in the upregulation of FOXO3a and Nrf2, pointing to a novel therapeutic target for breast cancer treatment." (PMID 32523652, 2020). "Insulin and insulin-like growth factor promote EMT in gastric, colon, hepatic and breast cancer." (PMID 32631390, 2020). "We found that insulin upregulated NR2F2 expression in MCF-7 and MDA-MB-231 breast cancer cells." (PMID 32631390, 2020). "Our study demonstrates that C-peptide, as an important bioactive peptide, plays a trigger role in the development and growth of breast cancer and it is independent of insulin." (PMID 33180852, 2020). "In human breast cancer patients, studies on the relationship between carbohydrate/glucose content in food and quantitative insulin characteristics are lacking." (PMID 31703648, 2019). "However, the results of our study provide further evidence of the importance of the insulin and IGF-1R pathway in breast cancer." (PMID 31455425, 2019). "Insulin and insulin-like growth factor-1 (IGF1) have important roles in breast cancer development." (PMID 31771180, 2019). "Despite the underlying mechanisms still remain poorly understood, proteins that have been previously related to cancer as well as to insulin signaling, such as APPL1 or Sam68, seem to positively mediate leptin induced phosphorylation of the main pathways activated by this hormone in breast cancer." (PMID 31380268, 2019). "Insulin increases the proliferation of ER+ MCF-7 cells (but not of ER− breast cancer cells) by increasing the release of growth factors that stimulate mitosis and inhibit apoptosis." (PMID 29415446, 2018). "Most of these findings, however, were based on small numbers of breast cancer patients and a single insulin measurement, which is not an ideal proxy for long-term insulin exposure 18]." (PMID 30092829, 2018). "In addition to estrogens, other molecules released from the adipose tissue such as insulin, IGF-I, inflammatory cytokines and adipokines also collectively promote breast cancer development and progression." (PMID 30567335, 2018). "A relationship between insulin and HER2 signaling was already demonstrated for breast cancer and could also be hypothesized in this context." (PMID 29662006, 2018). "We therefore investigated the role of insulin and the PI3K-dependence of SSH-1L/cofilin signaling in breast cancer cells and found that insulin treatment induced cofilin dephosphorylation without altering SSH-1L expression." (PMID 29029503, 2017). "In order to evaluate whether the DDR1 and IR co-localize in breast cancer cells, MCF-7 cells were plated onto coverslips, serum-starved for 24h and stimulated with either insulin or IGF-2 at a dose of 10nM for 5 and 20 min." (PMID 28591735, 2017).